GDF15 (growth differentiation factor 15)
Diseases named in the same sentence as GDF15 in open-access papers (continued):
Sharing a sentence is not in itself a finding about the gene and the disease.
tumor (continued). "In the case of neoplasms, GDF15 concentrations can significantly rise reaching values ranging between 10.000 and 100.000 pg/mL." (PMID 40868185, 2025). "Further evidence confirmed that tissue GDF15 levels were related to grade, presence of lymphovascular invasion, and higher tumor stages." (PMID 40868185, 2025). "GDF15 has demonstrated capabilities in inhibiting cellular proliferation, amplifying apoptosis rates, and suppressing tumor growth." (PMID 40144214, 2025). "We also observed that both GDF15 and log-transformed IL-6 concentration values positively and linearly correlated with tumor weight." (PMID 40124481, 2025). "High GDF-15 expression in tumours significantly reduces CD8+ cytotoxic and CD4+ T cells within the TME." (PMID 41294666, 2025). "When evaluated in terms of tumour size, only GDF15 expression demonstrated a statistically significant association, whereas no such relationship was observed for DJ-1 and MFGE8." (PMID 41009755, 2025). "ROC analyses were performed to evaluate the diagnostic discriminatory potential of DJ-1, GDF15, and MFGE8 gene expressions based on tumour grade." (PMID 41009755, 2025). "Nuclear fraction analysis further demonstrated that IRF5 predominantly localized to the nucleus in HNSCC tumor tissues compared to normal controls, and GDF15 overexpression enhanced this nuclear enrichment, whereas GDF15 knockdown reduced nuclear IRF5 levels." (PMID 41035818, 2025). "GDF15 has been intricately involved in several stages of oncogenesis, including tumor initiation, proliferation, metastasis, drug resistance, and recurrence." (PMID 40144214, 2025). "In cervical cancer (CCa), GDF15 promotes tumor proliferation by upregulating CyclinD1 and CyclinE1 while downregulating p21 via the PI3K/AKT and MAPK/ERK pathways in conjunction with ErbB2." (PMID 40868185, 2025). "Representative IHC images demonstrated the variation in GDF15 staining intensity between the tumor tissues." (PMID 40725563, 2025). "Given GDF15's involvement in tumor survival and immune modulation, clarifying its function in GBM radioresistance is critical." (PMID 41281763, 2025). "Although representative IHC images demonstrated a stronger and more heterogeneous GDF15 staining pattern in tumor tissues than in adjacent normal tissues, the difference was not statistically significant." (PMID 40725563, 2025). "Conversely, in TLS-deficient microenvironments, the relationship between GDF15 and TGFBR2 is associated with tumour invasion and subsequent metastasis." (PMID 39901202, 2025). "According to the TMA, the CD41-high expression group had significantly greater expression levels of LINC00183, ENO1, H3K18la, and GDF15 in CRC tumor tissues than the CD41-low expression group." (PMID 40775002, 2025). "GDF-15 (growth differentiation factor 15) is a stress-induced cytokine known to suppress immune responses and contribute to tumor immune evasion." (PMID 40001572, 2025). "Epidermal growth factor receptor and GDF-15 were excluded due to their irrelevance to her tumor genomics." (PMID 39786485, 2025). "Mechanistically, the functions of GDF15 are exerted via both tumor cell-intrinsic and -extrinsic signalings." (PMID 40144214, 2025). "RNA-seq identified robust induction of xenobiotic metabolism (CYP1A1, CYP1B1), oxidative/metabolic stress mediators (GDF15, TIPARP), and tumour-associated genes (FOSB, VGF), alongside repression of tumour suppressors (FAT1, LINC00472)." (PMID 41600570, 2025). "For PFS, tumor number (HR, 1.512; 95% CI, 1.008-2.268; p = 0.046), extrahepatic metastasis (HR, 1.644; 95% CI, 1.064-2.540; p = 0.025), and serum GDF15 (HR, 1.521; 95% CI, 1.014-2.283; p = 0.043) were independent predictors." (PMID 40677718, 2025). "Tumor tissues from GDF15-overexpressing immunocompetent mice after irradiation were collected for further analysis." (PMID 41281763, 2025).
tumor (continued). "The dual function of GDF15 as both a tumor-promoting factor and a key player in metabolic dysregulation makes it an attractive target for novel therapeutic strategies." (PMID 40868185, 2025). "Our results showed that NAG-1/GDF15 enhances the effects of quercetin, a polyphenol known for its anti-tumor properties, while silencing NAG-1/GDF15 with siRNA reduced quercetin’s efficacy." (PMID 40316530, 2025). "CHI3L1, mainly produced by infiltrating M2 macrophages in the tumor microenvironment, induced expression and secretion of growth differentiation factor 15 (GDF15) in tumor cells." (PMID 40313579, 2025). "GDF-15, a stress-induced cytokine produced by peripheral tissues and/or tumour cells, exerts its effects by binding to the glial cell line-derived neurotrophic factor family receptor alpha-like (GFRAL) receptor in the brainstem." (PMID 41294666, 2025). "For instance, oxaliplatin-induced immunogenic reactions in CRC are mediated by suppressed GDF-15 secretion from tumour cells, activating tumour immunity." (PMID 41294666, 2025). "For PFS, the correlative factors were tumor number (p = 0.018), extrahepatic metastasis (p = 0.005), and serum GDF15 (p = 0.013)." (PMID 40677718, 2025). "GDF-15 also exerts an immunosuppressive effect on T lymphocytes and dendritic cells (DCs), preventing T-cell adhesion and migration into the tumour microenvironment (TME)." (PMID 41294666, 2025). "In the context of PCa bone metastases, osteocyte-derived GDF15 promotes tumor growth by upregulating early growth response 1 (EGR1) expression through the GFRAL pathway." (PMID 40868185, 2025). "Tumor-derived GDF-15 inhibits the adhesion and movement of effector T-cells into the tumor microenvironment." (PMID 40732268, 2025). "In contrast, SM-2 treatment down-regulated GDF15 expression in cocultured tumor cells, suppressed ROS levels, and reduced expression of Nrf2 and SOD2." (PMID 41035818, 2025). "ROC analyses were performed to evaluate the diagnostic performance of the DJ-1, GDF15, and MFGE8 genes in discriminating tumour diameter." (PMID 41009755, 2025). "Elevated GDF-15 levels in the TME inhibit the immune response against tumours, facilitating immune escape and contributing to ICI resistance." (PMID 41294666, 2025). "In vivo bioluminescence imaging showed that rhGDF15 stimulation increased tumor burden in FaDu xenografts coinjected with mesenchymal stem cells (MSCs), and similar results were observed in GDF15 knockout animals." (PMID 41035818, 2025). "In this context, GDF15 functions as a multifaceted regulator influencing metabolism, inflammation, and tumor biology." (PMID 41009692, 2025). "This work clarifies GDF15’s critical function in fibroblast–tumor cell interactions in 3 key ways: First, GDF15 promotes the growth and invasion of HNSCC cells by up-regulating PCLAF expression via IRF5." (PMID 41035818, 2025). "Using the SW480 stable cell line, we performed an in vivo xenograft model to assess the effects of NAG-1/GDF15 expression on tumor development." (PMID 40316530, 2025). "GDF-15, produced by tumour cells, can act in a paracrine manner within the tumour microenvironment, influencing surrounding stromal and immune cells." (PMID 41294666, 2025). "Following CRC microarray research, we discovered that, in contrast to normal colon tissues, GDF15 expression was increased in CRC tissues, and was closely associated with poor tumor prognosis." (PMID 40775002, 2025). "Previous studies have demonstrated that GDF15 is rapidly upregulated following radiotherapy and other cellular stresses in multiple tumor types, where it functions as an adaptive survival factor supporting treatment resistance 54-56." (PMID 41281763, 2025). "While these findings are encouraging, significant gaps remain in our understanding of the precise role of GDF15 across different tumor types and stages." (PMID 40868185, 2025). "A phase 2 study of ponsegromab enrolled patients with elevated GDF-15 levels and selected tumour types." (PMID 41294666, 2025).
tumor (continued). "GDF15 modulates tumor progression through PI3K/AKT, MAPK/ERK, and SMAD2/3 signaling, thereby promoting epithelial-to-mesenchymal transition, metastasis, immune evasion, and chemoresistance via Nrf2 stabilization and oxidative stress regulation." (PMID 40868185, 2025). "GDF15 promotes tumor cell proliferation and invasion by upregulating STAT3 phosphorylation or by activating ErbB2, which is central to the PI3K/AKT and mitogen-activated protein kinase (MAPK) pathways." (PMID 40868185, 2025). "In vivo limiting dilution assays revealed that GDF15 silencing in CAFs markedly reduced tumor-initiating capacity in PDX-1 mice, as evidenced by higher tumor-free survival." (PMID 41035818, 2025). "In pancreatic cancer (PC), the autocrine GDF15-GFRAL axis drives tumor growth and metastasis, promoting progression and therapeutic resistance through pathways involving nuclear receptor NR5A2 and p38 MAPK." (PMID 40868185, 2025). "The tumor suppression activity of NAG-1/GDF15 and pro-NAG-1/GDF15 was directly examined with a xenograft mouse model." (PMID 40316530, 2025). "GDF-15-targeted therapies should be evaluated using a tumour-agnostic approach to treat cachexia and enhance immunotherapy efficacy." (PMID 41294666, 2025). "Overall, GDF-15 plays a critical role in suppressing T-cell function and contributes to an ‘immune-cold’ tumour phenotype." (PMID 41294666, 2025). "Some tumour types demonstrated a positive correlation between GDF-15 mRNA levels and immune signatures." (PMID 41294666, 2025). "Specifically, SM-1 enhances the stability of the GDF15–GFRAL complex, thereby activating a GDF15-mediated, tumor-promoting oxidative stress response." (PMID 41035818, 2025). "Pregnancy, exercise, aging, organ failure, inflammatory disease, neoplasia, cancer cachexia and mitochondrial diseases are only some of the conditions where augmented circulating levels of GDF15, in the order of ng/mL, have been detected." (PMID 40464681, 2025). "Immunohistochemical analysis of tumor tissue from the xenograft model similarly revealed stronger GDF15 staining in the BMN673-treated SK-CO-1 groups compared to the controls." (PMID 41266732, 2025). "Decreased GDF-15 levels in tumour specimens were correlated with T-cell infiltration, suggesting an immunosuppressive effect of GDF-15 on tumour immunity." (PMID 41294666, 2025). "Considering that inflammation is very common previously and concomitantly to tumor development, GDF15 is supposed to be involved in the initiation and progression of tumor." (PMID 40144214, 2025). "To further evaluate how GDF15 affects neutrophil function, we treated neutrophils with conditioned tumor cell supernatants." (PMID 41035818, 2025). "Conversely, elevated GDF-15 levels in the TME inhibit the host immune response against tumours, facilitating immune escape and contributing to resistance to immunotherapies, including ICIs." (PMID 41294666, 2025). "Raised levels of TAMs enhance FAO in tumor cells by producing growth differentiation factor 15 (GDF15), which leads to resistance of GC cells to 5-FU." (PMID 40514365, 2025). "MIC-1 (GDF15) and GRN are associated with tumor-induced immune tolerance and inflammation, while MERTK is a receptor tyrosine kinase involved in the clearance of apoptotic cells and immune suppression." (PMID 40805206, 2025). "Growth differentiation factor 15 (GDF-15) is a stress-induced cytokine produced by tumour cells and peripheral cells." (PMID 41294666, 2025). "Patients with RCC and elevated GDF-15 levels in tumor tissue exhibit a more favorable prognosis compared to those with lower levels." (PMID 39000420, 2024). "Our data suggest that increased VEGF and GDF15 lead promoting tumor growth via immune suppression of patient PBMC." (PMID 38197259, 2024). "NAG-1 (also known as GDF15) is a putative tumor suppressor whose expression can be induced by drug treatment." (PMID 39288289, 2024).
tumor (continued). "They showed that a high level of GDF-15 expression in the tumor tissue and high levels of GDF-15 in the plasma correlated with an increased risk of recurrence and reduced overall survival." (PMID 38668313, 2024). "In our studies, we showed a significant (p < 0.05) increase in expression of GDF-15 levels in tumor bearing mice compared to tumor-free mice." (PMID 39394174, 2024). "It seems that GDF15 is a crucial player in the tumor microenvironment and thus the GDF15 protein is a promising target for drug discovery." (PMID 39643709, 2024). "Cytokines, including CCL2, CCL5, CCL18, TGFB1, and GDF15, are produced by tumor cells and attract immune cells, such as macrophages and lymphocytes, from the blood and bone marrow into the tumor microenvironment." (PMID 39272860, 2024). "Consistent with the results of single‐cell data, MDK signalling, HGF signalling, chemerin signalling, and GDF15 signalling were also observed to be hyperactive signals primarily sent by the tumour cells based on the ST data." (PMID 38318640, 2024). "Further efficacy assessments of the neutralizing antibody KY-NAb-GDF15 were conducted using tumor animal models." (PMID 39172988, 2024). "In contrast, endurance exercise performance is enhanced in tumor-bearing mice treated with GDF15 neutralizing antibodies." (PMID 39480267, 2024). "GDF15 signaling is an important player in the maintenance of an immunosuppressive microenvironment in tumors, thus facilitating tumor growth and metastasis." (PMID 39643709, 2024). "In conclusion, our study is the first to use CRISPR/Cas9 nanocapsules to knockout GDF15 in tumor cells to enhance the immune cell‐mediated killing of tumor cells and promote the tumor‐killing effect of PD1 antibodies." (PMID 38704691, 2024). "Consistent with previous reports GDF15 was observed to be upregulated in CRC tumor samples in comparison with normal tissue or epithelial cells by both TCGA COAD and scRNA epithelial transcriptomic analyzes respectively." (PMID 39103698, 2024). "Nevertheless, the cooperation between YKL-40 and GDF-15 provides a compelling illustration of the significance of the interplay between macrophages within the tumor microenvironment." (PMID 39000420, 2024). "From an oncology perspective, a dual role has been proposed for GDF15, with its inhibition of carcinogenesis in normal tissues during the early stages of tumor development and its promotion of tumors at later stages." (PMID 39108882, 2024). "Collectively, our findings suggest that using nanocapsules to knockout GDF15 in orthotopic HCC xenografts in vivo can markedly inhibit tumor progression and extend survival." (PMID 38704691, 2024). "According to them, higher hepcidin and GDF-15 levels contributed to metastases, tumor recurrence and shorter OS." (PMID 39272712, 2024). "GDF15 protein expression in spontaneous HCC tumor tissues was also downregulated, indicating GDF15 gene disruption." (PMID 38704691, 2024). "The GDF15 protein is highly expressed in tumor cells themselves and in the cells surrounding the tumor." (PMID 39643709, 2024). "Measurement of expression of GDF-15 gene showed significant increase in expression levels in tumor bearing mice." (PMID 39394174, 2024). "We investigated the expression of GDF15 in 31 tumor and normal tissue samples from The Cancer Genome Atlas (TCGA) database and found that 26 tumors had higher GDF15 expression than normal tissues." (PMID 38704691, 2024). "The tumor tissue sections obtained from mice undergoing SNCSS(Cas9/sgGDF15) treatment exhibited decreased expression levels of GDF15 and Ki‐67, as revealed by immunohistochemical analysis, compared to the control groups." (PMID 38704691, 2024). "This inhibition results in reduced lymphocyte infiltration at the tumor site when GDF-15 tissue levels are elevated." (PMID 39000420, 2024).
tumor (continued). "In cervical cancer, GDF15 binds to the ErbB2 receptor and promotes the proliferation of tumour cells by up-regulating cyclin D1 and cyclin E1 expression and down-regulating p21 expression through the PI3K/Akt and MAPK/ERK signalling pathways." (PMID 37093513, 2024). "Immunohistochemical analysis demonstrated a notable reduction in the number of GDF15‐positive tumor cells (indicated by brown staining) in samples treated with SNCSS(Cas9/sgGDF15), which is in agreement with the results obtained from western blotting." (PMID 38704691, 2024). "The interaction of YKL-40 and GDF-15 has been demonstrated to promote tumor invasion and to upregulate PD-L1 expression in tumor cells." (PMID 39000420, 2024). "The tumor volume was weakly to moderately positively correlated with the GDF15 transcript levels in the primary cells, as well as the GDF15 concentrations in the CCS." (PMID 39272860, 2024). "The SNCSS capable of targeting HCC are loaded with Cas9/sgGDF15 and specifically edited the GDF15 gene in HCC tumor cells through tail vein injection in mice." (PMID 38704691, 2024). "GDF-15 contributes to immune evasion by inhibiting T-cell activity within the tumor microenvironment, potentially diminishing the efficacy of immune checkpoint inhibitors (ICIs)." (PMID 39766045, 2024). "GDF-15 is known to be released by a variety of cell types, including tumor cells of different histologies." (PMID 39283723, 2024). "Next, we tested the gene editing efficiency of GDF15 in the tumor tissues of mice in all treatment groups using NGS, western blotting, and T7E1 mismatch detection assays." (PMID 38704691, 2024). "An increased GFRAL expression promotes tumor growth in a dose-dependent fashion with increasing GDF-15 concentration." (PMID 39000420, 2024). "GDF-15 was shown to be expressed/released by tumor cells of different histological origin and, in the context of tumor microenvironment, by tumor-associated macrophages and fibroblasts." (PMID 39283723, 2024). "Based on currently available literature, the role of GDF-15 on tumor onset and progression is far from being elucidated." (PMID 39283723, 2024). "The mRNA levels of CCL18 and GDF15 were positively correlated with tumor volume in the tumor samples, and the other cytokines were also expressed in the tumor samples." (PMID 39272860, 2024). "Among these markers, only the mRNA amount of GDF15 correlated with tumor volume (estimate 1.637, standard error 0.282)." (PMID 39272860, 2024). "Moreover, clinicopathological characteristic analysis indicated that higher GDF15 expression was positively associated with invasion depth (p = 0.002), nodal involvement (p = 0.003), stage (p = 0.010), lymphatic invasion (p = 0.050), and tumor size (p = 0.049)." (PMID 36769245, 2023). "In vivo, GDF-15 expression translates into reduced immune infiltration in syngeneic and humanized tumor models." (PMID 37474523, 2023). "High levels of growth differentiation factor 15 (GDF15), which is produced by TAMs, also impair the chemosensitivity of tumor cells via enhancing fatty acids β-oxidation." (PMID 36982677, 2023). "GDF15 is a stress-induced cytokine secreted by tumor cells that is affected by tumor-promoting inflammation and immune infiltration." (PMID 36472770, 2023). "In this study, we show that tumor-derived GDF-15 inhibits the LFA-1/ICAM-1 axis in T cells and T cell migration into tumor tissue." (PMID 37474523, 2023). "WFDC2 can be measured as a tumor marker in Japan, and thus, GDF15 was excluded and WFDC2, CHI3L1, and KRT19 were used as the variables of classification." (PMID 36331721, 2023). "GDF15 downregulation contributed to tumor viability and aggressiveness and was shown to significantly hinder ferroptosis in ccRCC." (PMID 38082448, 2023). "Tumor-bearing animals were randomized by bioluminescence in vivo imaging on day 5, and subsequently treated with either anti-PD-1, or anti-GDF-15, or both, or isotype control antibody." (PMID 37474523, 2023).